IL18 (interleukin 18)
Diseases named in the same sentence as IL18 in open-access papers (continued):
Sharing a sentence is not in itself a finding about the gene and the disease.
COVID-19 (continued). "To functionally test the role of cytokines on the viability of lymphocytes, we treated PBMCs isolated from healthy donors with selected groups of cytokines (e.g., IL-10, IL-15, IL-18, IL-8, IL-6, IL-1RA, IL-2RA, IL-4) for 36 h, using the maximum doses detected in COVID-19 serum." (PMID 34103487, 2021). "Indeed, activation of CASP1 by activating inflammasomes in response to the SARS-CoV-2 infection activates IL1B and IL18 and contributes to hypercytokinemia in COVID-19 patients." (PMID 34975885, 2021). "Moreover IL-1β, IL-2, IL-5, IL-18, TNFα, and GM-CSF became detectable in all the samples following co-culture between resting PBMCs from COVID-19 patients and DPSCs." (PMID 33634100, 2020). "Furthermore, ferritin correlates with sCD163, the soluble form of the CD163 receptor, which is mainly located on the surface of monocytes and macrophages, and also with interleukin-18 (IL18), suggesting a mechanistic link between macrophage activation and cytokine release in COVID-19." (PMID 41373577, 2025). "Thus, evaluating the tissue expression of IL-6, IL-1β, and IL-18 in a sensory nerve could provide information about neuroinflammation related to neuropathic pain in post-COVID-19 conditions." (PMID 41516235, 2025). "The current study documented that - 607 SNP of IL-18 was not linked to mortality in COVID-19." (PMID 36999046, 2023). "Considering that increased IL-18 levels were found in patients with a more severe COVID-19 phenotype, we could speculate that an inappropriate initial response against SARS-CoV-2 in rs1834481-G allele carriers may predispose to virus persistence, and subsequently to dysregulated immune responses." (PMID 37766191, 2023). "SARS-CoV-2 infection could trigger the activation of NLRP3 inflammasome to release IL-1β, IL-18, and gasdermin D and, consequently, damage to lung tissue in patients with COVID-19, suggesting the dysregulation of NLRP3 inflammasome might contribute to the severity of COVID-19." (PMID 36960050, 2023). "However, antiviral and inflammatory responses mediated by IL-18 are strongly affected by other cytokines and the immune cell milieu; therefore, further investigation is needed to completely unravel the role of IL-18 in COVID-19." (PMID 37766191, 2023). "In this study, we analyzed the IL-18 polymorphism between survivors and non-survivors of COVID-19." (PMID 36999046, 2023). "Therefore, a reduction in plasma concentrations of IL-18 and IL-1RA may be beneficial for the cardiovascular health of COVID-19 survivors." (PMID 36835948, 2023). "IL-18 is a proinflammatory cytokine released downstream of the activation of innate immune pathways, resulting in the formation of inflammasomes; it has already been correlated with a poor COVID-19 prognosis, since increased IL-18 levels have been found in patients with severe disease." (PMID 37766191, 2023). "Taken together, the IgM glycosylation profile closely correlates with COVID-19 severity on clinical and serological parameters and the cytokines IL-16 and IL-18 may play a role in controlling downstream glycosyltransferase expression in plasma blasts during COVID-19." (PMID 37398192, 2023). "Additionally, circulating Tregs from patients with severe COVID-19 exhibit decreased amphiregulin expression, suggesting that some of IL-18’s effects may be mitigated by other COVID-19 cytokine storm components." (PMID 36992283, 2023). "Traditionally, activation of the NLRP3 inflammasone is regarded to be the main inducer of pathogenic pro-inflammatory cytokines IL-1β, IL-18 and IL-6 during COVID-19, but it has become clear that multiple non-conical pathways can contribute and indeed become the dominate inducers of IL-1β." (PMID 35244141, 2022). "Thus, a possible mechanistic explanation for myopericarditis after COVID-19 mRNA vaccine could be cardiac injury mediated by vaccination-triggered excessive IL-18 production and Th1 immunity activation as a consequence." (PMID 35251049, 2022).
COVID-19 (continued). "Given the fact that 16- to 29-year-old males showed a higher incidence of COVID-19 vaccine-related myocarditis than other groups, we speculate that young men could have a stronger IL-18 production and Th1 immune response compared to females, although this requires further investigation." (PMID 35251049, 2022). "For example, vitamin D could reduce ARDS (acute respiratory distress syndrome) in the context of COVID-19 by suppressing the expression of target genes, such as IL18, CXCL9 and CXCL10, that mediate the cytokine storm associated with the severe form of the disease." (PMID 35055093, 2022). "Furthermore, IL-18, which increases in COVID-19 patients, has been described to potentiate CXCL10 expression; a chemokine reported to inhibit cell proliferation and promote the death of endothelial cells; this process being prevented by administrating a caspase inhibitor." (PMID 35066575, 2022). "Thus, circulating NK cells and T cells might be activated directly by elevated IL-18 and IL-27 in the patient with COVID-19 vaccine-related myopericarditis." (PMID 35251049, 2022). "Thus, excessive activation of innate immune responses mediated by IL-18, an IL-1 family member, may contribute to myopericarditis development after COVID-19 mRNA vaccination." (PMID 35251049, 2022). "Interestingly, IL-18 can contribute to the pathology of COVID-19 by altering MAIT cell function." (PMID 35265086, 2022). "In addition, an increased IL-18 level is found in the sera of hospitalized patients with COVID-19." (PMID 34360684, 2021). "Many cytokines are involved in the pathogenesis of COVID-19, and IL-18 may also be relevant." (PMID 33732720, 2021). "Furthermore, the study showed that the levels of IL-18, a pro-inflammatory cytokine produced by multiple intestinal cells and the intestinal nervous system, were increased in the sera of COVID-19 patients compared with those in influenza patients and healthy individuals." (PMID 34161373, 2021). "Moreover, IL-18 and IL-1R7 are found to be highly expressed in cell-to-cell communication among immune cells in COVID-19 patients and elevated IFNγ was observed in COVID-19 patients in line with increased IL-18 levels." (PMID 33823154, 2021). "In addition, circulating Tregs from severe COVID-19 patients actually show reduced amphiregulin expression, indicating that some aspects of IL-18 effects may be counteracted by other components of the COVID-19 cytokine storm." (PMID 34433692, 2021). "Colchicine works by interfering with COVID-19 related manifestations such as hyper-inflammation, and inhibits inflammasome activation, neutrophil chemotaxis and the production of pro-inflammatory cytokines such as interleukin-1beta (IL-1β) and interleukin-18 (IL-18)." (PMID 33681243, 2021). "Finally, alterations in the production of IL-10 and IL-18 by T lymphocytes might be involved in COVID-19 pathogenesis." (PMID 33634100, 2020). "Moreover, besides IL-1 and IL-18 production-related functions, DMGs in ‘Monocyte2’ are also enriched in the functions of ‘phagocytosis’ and ‘endocytosis’, indicating the antigen presentation function of this cluster, which is specifically enriched in COVID-19 monocytes." (PMID 37425926, 2025). "Multiple studies show high levels of proinflammatory cytokines such as IL-1, TNF, IFNs, IL-6, IL-8, IL-18, IL-17α, G-CSF, and GM-CSF, as well as chemokines, such as MCP-1, IP-10, MIP-1α, CXCL10, CCL2, CCL4, CCL14, CCL19, and CCL25 in severe cases of COVID-19." (PMID 40076291, 2025). "These collective data suggested that proinflammatory mediators characteristic of severe disease, most notably IL-18, limited the induction and recall of highly cytotoxic SARS-CoV-2–specific CD8+ T cells in patients with acute COVID-19." (PMID 39847442, 2025). "In our study, interleukins (IL-1 α, IL-7, IL-17, and IL-18) and chemokines (CCL11 and CXCL1) were found increased in COVID-19-only." (PMID 41516165, 2025).
COVID-19 (continued). "As expected, plasma concentrations of several inflammatory mediators, including IL-1α, IL-6, IL-18, IP-10, HGF, MCP-3, and M-CSF, were elevated in patients with acute COVID-19, especially those with severe disease." (PMID 39847442, 2025). "The levels of proinflammatory cytokines and chemokines (IL-8, IL-18, CCL5) were higher in males with severe COVID-19, and the T cell response was less robust than that in females." (PMID 39507250, 2024). "In pathological conditions like macrophage activation syndrome (MAS), COVID-19 and inflammatory bowel diseases (IBD), IL-18 is upregulated and plays an important role in the disease development." (PMID 38983847, 2024). "The seven pro-inflammatory cytokines (IL-6, IL-8, IL-15, IL-18, IL-27, IFN-γ, and TNF-α) and two anti-inflammatory cytokines (IL-1RA and IL-10) were elevated in COVID-19 patients compared to healthy controls." (PMID 39408907, 2024). "The MCP-1, IL-18, and IFN- γ levels were higher in COVID-19 patients than in vaccinated HCWs, while IL-22 levels increased in the vaccinated HCWs group." (PMID 39258622, 2024). "During COVID-19, strong activation of the NLRP3-inflammasome and caspase-1 is induced with subsequent release of IL-1β and IL-18, although these cytokines remain difficult to detect in patient’s blood." (PMID 39882243, 2024). "A comparative analysis of patients diagnosed with COVID-19, COVID-19 with concurrent maculopapular rash, or DRESS found that there were similar elevations of CXCL9, CXCL10, CXCL11, IFN-γ, IL-10, TNF-α, and IL-18 across the three groups." (PMID 39318634, 2024). "Previous studies found a positive correlation between increased serum levels of IL-1β, IL-18, and LDH in COVID-19 patients and the severity of the disease, suggesting the involvement of inflammasomes in the pathogenesis of SARS-CoV-2." (PMID 38399989, 2024). "Circulating IL-18 was slightly higher in severe compared to moderate COVID-19 (p<0.05), but lower in IMV-COVID-19 compared to severe COVID-19 (p<0.05)." (PMID 39882243, 2024). "As all COVID-19 patients in our study were hospitalized, it is reasonable to consider IP-10, HGF, and IL-18 as biomarkers of disease severity in SARS-CoV-2 infected patients." (PMID 38486975, 2024). "An in-depth understanding of the exact role and regulatory mechanism of IL-18 and IL-1β in SARS-CoV-2 infection is very important for the formulation of targeted treatment strategies and the effective management of COVID-19." (PMID 38399989, 2024). "Analysis of cytokine profiles showed increased plasma levels of IP-10, HGF, VEGF-A, IL-7, IL-18, and MCP-1/CCL2 in COVID-19 patients." (PMID 38486975, 2024). "In this study, we first found that the gene expression of NLRP3 and IL-1β was downregulated in the CD14+ and CD16+ monocytes from COVID-19 patients, while MARCH7 and IL-18 declined only in the CD16+ monocytes." (PMID 38004809, 2023). "Our data demonstrate that the serum levels of IL-12, IL-13, IL-18, and IFN-γ are disturbed in patients with severe COVID-19 compared to mild and moderate cases." (PMID 37373331, 2023). "For example, elevated levels of IL-1β, Casp1p20, IL-1RA, IL-18, and lactate dehydrogenase (LDH) were detected in severe COVID-19 patients’ plasma." (PMID 37508374, 2023). "In human COVID-19, expression of IL1B and IL18 shifted from mostly alveolar macrophages to SPP1/MERTK+ macrophages." (PMID 37737611, 2023). "In a small cohort of seven MIS-C patients, differentiation between COVID-19 and MIS-C patients was achieved using a combination of IL-10, IL-1RA, IL-18, IL-6, TNF and IFN-gamma." (PMID 37685502, 2023). "The lung and spleen tissue obtained from patients who died from COVID-19 exhibited higher densities of cells expressing NLRP3, IL-18, NF-κB and gasdermin D, and even HMGB-1, than age-matched controls who had died unexpectedly, but free of SARS-CoV-2-infection." (PMID 38439942, 2023).
COVID-19 (continued). "The mediators IL-1β, IL-6, IL-10, TNF-α, IL-8/CXCL8, IL-1RA, IL-18/IGIF, and sTNFR1 were all increased in patients with COVID-19 and followed the rate of elevation as clinical worsening progressed." (PMID 36851766, 2023). "Since caspase-1-independent pathway also gives rise to enhanced IL-18 secretion, the relationship between NLRP3 inflammasome activation and COVID-19 development is an important subject to be further addressed." (PMID 37251383, 2023). "Patients with severe COVID-19, as evidenced in our study, release a large amount of pro-inflammatory cytokines (IFN-α, IFN-γ, IL-1β, IL-6, IL-12, IL-18, IL-33, TNF- α, and TGF- β)." (PMID 37408032, 2023). "Following overnight stimulation with IL-12 and IL-18, IFN-γ production was only significantly decreased in patients with severe COVID-19 compared to healthy donors (p<0.0001), but return closed to the normal production at the second time-point (Pt2)." (PMID 37342247, 2023). "In this prospective case-series of 120 COVID-19 patients, the assessment at ED admission of the urinary biomarkers for kidney injury (NGAL, KIM-1, IL-18) was of limited value to predict AKI." (PMID 36983566, 2023). "In cases of sepsis, including bacterial sepsis and viral conditions like COVID-19 (coronavirus disease-2019), aberrant activation of the NLRP3 inflammasome has also been documented mostly through the measurement of increased plasmatic concentrations of IL-1β and IL-18." (PMID 38140660, 2023). "The serum levels of IL-12, IL-18, and IFN-γ differed even more in the severe compared to moderate and mild forms of COVID-19." (PMID 37373331, 2023). "The serum levels of IL-12, IL-18, and IFN-γ were increased in mild COVID-19 compared to the control group." (PMID 37373331, 2023). "High levels of IL-1β, IL-18 and LDH positively correlate with disease severity in COVID-19 patients, suggesting that inflammasomes participate in SARS-CoV-2 pathogenesis." (PMID 37920468, 2023). "Gene set enrichment analysis of DEGs showed upregulation of IL-18 (P < 0.001), TNF (P < 0.0001), and VEGFA-VEGFR2 signaling pathways (P = 0.002) in COVID-19 subjects." (PMID 36881624, 2023). "Previous work has shown that IL1B, IL18, and CXCL10 are induced by SARS-CoV-2 infection and contribute to COVID-19 pathogenesis." (PMID 37737611, 2023). "The serum level of only IL-18 was increased, while IL-12 and IFN-γ appeared to be unaffected in severe COVID-19 when compared to the control group." (PMID 37373331, 2023). "MAS cytokine storms exhibited higher IL-6, IL-18, IFN-γ, TNF-α, and CXCL9 than severe COVID-19, with IFN-γ, IL-18, and CXCL9 being significantly lower in COVID-19." (PMID 35401519, 2022). "Levels were most pronounced in samples taken at early time points post onset of COVID-19 symptoms with the exception of TNF-α and IL-18 which remained high in all hospitalised patients or even increased (IL-18) in samples taken at day 21-30 post symptoms." (PMID 36275702, 2022). "Patients with severe COVID-19 can progress to ARDS, which is usually accompanied by inflammatory biomarkers, especially IL-1β, IL-6, IL-8, IL-18 and TNF." (PMID 36052163, 2022). "Copious interleukin (IL)-1β, IL-18 and lactate dehydrogenase (LDH) correlate with COVID-19 severity in patients, suggesting a role for inflammasome activation and pyroptosis in pathology." (PMID 35483404, 2022). "In addition, NK cells obtained from severe COVID-19 patients with a long disease duration were phenotyped with a low expression of cytotoxic molecules and had a lower in vitro cytokine production upon IL-12+IL-18 stimulation, all indicative of an exhausted phenotype." (PMID 36275702, 2022). "In post-COVID-19 patients, some plasma cytokines (i.e. TNF-α, IL-18, CXCL8, CXCL10, CCL2, CCL3, and CCL4) remained higher than in HCs, but levels were much lower as compared to hospitalised patients." (PMID 36275702, 2022).
COVID-19 (continued). "In an additional experiment in which NK cells were stimulated in vitro for 18 hours with IL-12+IL-18, we confirmed the defective cytokine-induced IFN-γ production in patients with severe COVID-19 disease symptoms." (PMID 36275702, 2022). "NLRP3 inflammasome activation primed and stimulated host inflammatory response, and the inflammatory cytokines (including IL-1β, IL-2, IL-6, IL-8, IL-18, and TNF-α) have been identified to be related to disease severity in COVID-19 patients." (PMID 34979342, 2022). "In peripheral blood immune cells and tissues of COVID-19 patients, activated NLRP3 inflammasome, caspase-1, and high levels of GSDMD-NT were found, as well as elevated expression of IL-1β and IL-18 in serum." (PMID 36532040, 2022). "Patients with COVID-19 showed a significant positive correlation (p < 0.001) between their CO-RADS score and their WBCs, CRP, and interleukins (IL-1, IL-4, IL-6, IL-18, and IL-35) levels." (PMID 36675695, 2022). "This framework releases large amounts of pro-inflammatory cytokines, as in COVID-19, including IL-6, TNF, IL-1β, IL-12, IL-17, IL-18, IP-10, IFN-γ, CCL2 and CCL5." (PMID 35843719, 2022). "Flow cytometry analysis confirmed increased intracellular IL-18 and NLRP3 inflammasome expression in CD14+ monocytes of the patient with COVID-19 vaccine-related myopericarditis." (PMID 35251049, 2022). "While IFN-α and IFN-β were undetectable, IL-10, IL-17A and IL-18 were variably detected in COVID-19 BALF, with higher RNA and/or protein levels of IL-6, MCP-1 and IL-33 and lower IL-6 receptor (IL-6R) observed in COVID-19 BALF compared to healthy BALF19,20." (PMID 35589689, 2022). "IL-18, along with other cytokines (IFN-γ, IL-1, IL-6, TNF), are elevated in cytokine storm and are thought to have central immunopathologic roles in COVID-19." (PMID 36510222, 2022). "An upsurge of IL-1β, IL-18, and LDH (Lactate dehydrogenase) has been reported in sera of COVID-19 patients, which hints the involvement of the inflammasome network." (PMID 33467177, 2021). "Whether promoting interleukin-18 or its consequences, such as IFNγ, might be helpful to prevent or treat COVID-19 could be considered, given these treatments are available, and a small case series suggested promising results of using IFNγ in critically ill COVID-19 patients." (PMID 34911594, 2021). "Compared with severe COVID-19 patients, active AOSD patients had 68-fold higher levels of IL-18 and 5-fold higher levels of ferritin (both p<0.001)." (PMID 34367188, 2021). "IL-18 levels at the cut-off value 190.5pg/mL had the highest discriminative power for active AOSD and severe COVID-19, with AUC 0.948, sensitivity 91.3%, specificity 95.8%, and accuracy of 91.5% (p<0.005)." (PMID 34367188, 2021). "Patients with COVID-19 showed high mRNA expression and secretion of cytokines, IL-1β, IL-6, TNF-α, and IL-18, but showed a significant reduction in IL-6 and IL-1β after treatment with nanocurcumin." (PMID 34025433, 2021). "Significantly higher levels of galectin-3, galectin-9, IL-1β, IL-1Ra, IL-10, IFN-α2, IL-6, IL-18, and TNF-α were observed in severe COVID-19 and active AOSD patients compared with HC (all p<0.001)." (PMID 34367188, 2021). "Compared with HC, IL-18, IL-6, and ferritin were markedly elevated in active AOSD patients (Log2 fold changes, 8.86, 8.34, and 4.30, respectively) and in severe COVID-19 patients (Log2 fold changes, 2.73, 6.97, and 1.97, respectively)." (PMID 34367188, 2021). "Our COVID-19 patients had significantly higher levels of IL-1β, IL-1Ra, IL-10, IFN-α2, IL-6, IL-18, and TNF-α than HC." (PMID 34367188, 2021). "Cytokine response in severe COVID-19 patients was clearly marked by elevated levels of pro-inflammatory cytokines, including IL-6, IL-8, MCP-1, and IL-18 compared to healthy donors." (PMID 33692788, 2021).